NOTCH3 (notch receptor 3)
Diseases named in the same sentence as NOTCH3 in open-access papers (continued):
Sharing a sentence is not in itself a finding about the gene and the disease.
tumor (continued). "The presence of NOTCH3 in tumor nuclei, presumably an indication of activation, was linked to a more aggressive disease phenotype and was associated with reduced survival following tumor resection." (PMID 39548190, 2025). "More NOTCH3 positivity was observed in high-grade tumours and was associated with a higher risk of mortality, thus indicating NOTCH3 as a potential reliable IHC marker for selecting BCa patients who may require more intensive follow-up." (PMID 41008920, 2025). "Furthermore, we found a significant association (p = 0.047) with Notch3 polymorphism A > G and elevated protein expression in tumor tissue and increased risk of CRC development." (PMID 41027955, 2025). "Interestingly, activating mutations in NRR and PEST domains of Notch3 have been described in several tumor cell lines, including an NRR mutation in a human TALL1 cell line that likely makes the S2 site more accessible to ADAM metalloproteases." (PMID 39684550, 2024). "Proteins associated with tumor progression or a bad prognosis such as WNT5A, MMP13, MMP3, telomerase, and NOTCH3 were upregulated while proteins associated with immune cell infiltration or pathway inhibitors/tumor suppressors such as FRZB, CD177, PPARG, and HRASLS2 were downregulated." (PMID 38504345, 2024). "Mechanistically, IGF2BP3 maintains NOTCH3 mRNA stability via suppression of CCR4-NOT complex-mediated deadenylation in an m6A-dependent manner, which sustains Notch3 signaling activation and increases the transcription of stemness-associated downstream genes, eventually promoting tumor metastasis." (PMID 37853162, 2023). "In favor of this role, we observed that loss of Notch3 induced an acceleration of tumor initiation." (PMID 36854682, 2023). "Cancer genome sequencing of the patient’s tumor tissue detected a NOTCH3 missense mutation which could provide an explanation for these clinical findings." (PMID 36749424, 2023). "This loss of Notch3 in epithelial cells during transformation may be associated with a tumor suppressive role of Notch3." (PMID 36854682, 2023). "NOTCH3 expression was also detected in the majority of vascular endothelial cells associated with tumors, which may facilitate tumor angiogenesis." (PMID 36382054, 2022). "NOTCH3 mutation may regulate the transcription of pTa and the activity of the NF-kB signaling pathway to promote tumor progression." (PMID 36497234, 2022). "Additionally, in the presence of TGFβ in the TME, NOTCH1 and ZEB1 cooperate and jointly cause inhibition of NOTCH3 expression, which consequently promotes tumour initiation and EMT." (PMID 34944837, 2021). "Nuclear NOTCH3 accumulation is associated with tumor recurrence in stage II and III CRC patients." (PMID 33452458, 2021). "In addition, Notch3 signaling in liver CSCs is supported by cancer-associated fibroblasts in the tumor microenvironment and maintains tumor cell self-renewal." (PMID 34195229, 2021). "To define the causative role of NOTCH3 expression in promoting ALDH1 activity that represents a universal functional marker of tumor stemness, chemoresistance, and metastasis, we performed an ALDEOFLUOR assay in vMCF-7Raf-1 1GX and vMCF-7Raf-1 1GXCRISPR-NOTCH3 cells." (PMID 30180881, 2018). "In line with a role of Notch3 in tumour associated endothelial cells, we observed an increase in CD31 and DLL4 expression in tumours from Notch3LacZ/LacZ mice, but no change in αSMA or PDGFRβ (Beta-type platelet-derived growth factor receptor), two pericyte markers." (PMID 28719575, 2017). "In contrast, Notch3-induced apoptosis in tumour-associated endothelial cells following DAPT treatment could explain at least partly the anti-angiogenic effect followed by tumour growth inhibition." (PMID 28719575, 2017). "We therefore conclude that, in TNBC, the loss of Notch3 expression may be one of the most important genetic traits of this tumor subtype." (PMID 27841855, 2016).
tumor (continued). "In twin slides, we could also observe that the same Hey1 positive tumor areas concomitantly expressed active Notch3, had increased tumor cell proliferation and presented loss of epithelial markers, suggesting a de-differentiation phenotype." (PMID 26213336, 2015). "Moreover, Notch3 has been associated with tumor proliferation." (PMID 33920054, 2021). "Re-introduction of Notch3 resulted in growth inhibition and activation of cellular senescence, suggesting that loss of Notch3 expression facilitates senescence induction and could play a critical role in tumor progression." (PMID 30515368, 2018). "Single-nucleus analysis reveals complex multicellular ecosystems, with NOTCH3-mediated signaling between tumor cells and myofibroblasts emerging as a potential therapeutic vulnerability." (PMID 41794038, 2026). "In vivo, NOTCH3 depletion synergized with anti-PD-L1 therapy to inhibit tumor growth and increase CD8+ T cell infiltration." (PMID 41808828, 2026). "Reports have identified a group of Notch3+ stem cells around blood vessels that can promote tumour initiation, enhance cell expansion ability and intensify tumour‐related angiogenesis." (PMID 40665579, 2025). "Immunofluorescence analysis demonstrated a significant upregulation of NOTCH3 expression in the tumor tissues of the group with MYBL2 overexpression." (PMID 40092688, 2025). "Notch3 deletion partially suppressed tumor development, likely due to redundancy or compensational upregulation of other Notch receptors." (PMID 39548190, 2025). "Functional rescue experiments showed that miR‐129‐2‐3p overexpression or NOTCH3 knockdown effectively counteracted the tumor‐promoting effects of LINC00958." (PMID 41090505, 2025). "Administration of NOTCH3 inhibitor with ASOs against SNORA74A exerts synergistic therapeutic effect on HCC tumor models." (PMID 40270470, 2025). "In vivo xenograft experiments using Ishikawa cells supported the in vitro findings, confirming that LINC00958 promotes tumor growth by modulating the miR‐129‐2‐3p/NOTCH3 axis." (PMID 41090505, 2025). "With IHC staining, we confirmed that E2 treatment decreased the Ki-67 positive tumor cells, reduced NOTCH3 expression, lessened M2 infiltration and increased CD8+ T cell infiltration." (PMID 40940884, 2025). "Utilizing multiple approaches, we demonstrated that depression accelerated tumor growth, correlating with reduced systemic estradiol levels and upregulated NOTCH3 expression." (PMID 40940884, 2025). "IHC analysis indicated that NOTCH3 knockdown suppressed tumor cell proliferation (fewer Ki-67+ cells) and promoted anti-tumor immunity (increased CD8+ T cell infiltration and diminished M2 macrophage accumulation) compared with controls." (PMID 40940884, 2025). "We found that protein expression was upregulated in 43.57%, 45%, 56.31%, and 42.71% of tumor tissue in Notch1, Notch2, Notch3, and Notch4, respectively." (PMID 41027955, 2025). "Collectively, SNORA74A mediated Notch3 signaling activation induces self‐renewal of liver CSCs and tumor propagation." (PMID 40270470, 2025). "To further determine in vivo function of NOTCH3 signaling, we performed subcutaneous tumor formation assays and found that NOTCH3 depletion remarkably reduced tumor growth." (PMID 40270470, 2025). "We then examined expression levels of NOTCH3 in HCC tumor and peri‐tumor tissues, liver CSCs and non‐CSCs, as well as in oncospheres and non‐sphere cells." (PMID 40270470, 2025). "Among its subtypes, NOTCH3 has garnered significant attention for its dualistic role in cancer, functioning as an oncogene in most contexts and as a tumor suppressor in others." (PMID 40940884, 2025). "On clinical correlation, Notch3 (rs1043994) A > G is associated with advanced disease stage in CRC, while Notch1 and Notch4 showed an association with depth of invasion and tumor grade, respectively." (PMID 41027955, 2025).
tumor (continued). "By examining the expression of individual Notch receptors in both PKC-Lfng and LPKC-Lfng pancreas tissues, we identified Notch3 as a functional Notch receptor for tumor initiation and progression from Lfng-expressing cells." (PMID 39548190, 2025). "Through metabolomic and lipidomic profiling, this study demonstrates that NOTCH3 activation influences lipid metabolism through the depletion of fatty acids, which are used by the tumor cells for FAO." (PMID 40502769, 2025). "Notch3 serves as a prominent receptor for the decision to adopt a luminal progenitor fate, and both tumor-suppressive and oncogenic roles for Notch3 have been identified in the mammary epithelium." (PMID 39890784, 2025). "Addition of exogeneous DLL4 resulted in enhanced tumor cell numbers via Notch2 and/or Notch3-mediated canonical pathway activation." (PMID 39951484, 2025). "Compared to the control group, serum levels of HSPA6 and NOTCH3 were significantly elevated in the CRC tumor group, whereas GPD1L, PKP2, and SMAD9 exhibited a marked decrease." (PMID 40796704, 2025). "FRα overexpression in murine αT3 gonadotroph tumor cells in vitro increased S-phase cells and cell proliferation, in part by activation of the NOTCH3 pathway." (PMID 40565361, 2025). "In OSCC, NOTCH3 is found in about one‐third of CAFs, especially near the tumor's edge, but is rarely expressed in cancer cells." (PMID 39928309, 2025). "A cooperative role of NRF2 and C/EBPβ (a transcription factor of the CCAAT/enhancer binding protein family) was described in generating tumor-specific enhancers that promote tumor initiation via NOTCH3 activation." (PMID 40369363, 2025). "Overall, this study identifies LINC00958 as a novel oncogenic lncRNA in EC, which facilitates tumor progression by sponging miR‐129‐2‐3p and enhancing NOTCH3 signaling." (PMID 41090505, 2025). "Different receptors have distinct roles; for example, NOTCH1 acts as a tumor suppressor, while NOTCH3 promotes tumor growth." (PMID 39928309, 2025). "The qPCR analysis quantitatively confirmed the upregulation of MFSD5, PARVA, PRSS3, OLFML2A, and NOTCH3 at the mRNA level in tumor tissues, with statistically significant differences compared to adjacent tissues." (PMID 40781483, 2025). "The lung metastasis model of BLCA further confirmed that NOTCH3 knockdown inhibited tumor metastasis in mice." (PMID 39557868, 2024). "The results demonstrated that NOTCH3 overexpression led to increased tumor growth, whereas its knockdown resulted in reduced tumor development." (PMID 39286249, 2024). "We further evaluated the effects of targeting NOTCH3 on tumor growth and metastasis in BLCA, as well as the regulation of SPP1-PI3K/AKT axis." (PMID 39557868, 2024). "With regard to the other members of the NOTCH gene family, NOTCH2 and NOTCH3 reflected similar expression trends across tumor types." (PMID 39737401, 2024). "We found that the correlation between the expression of certain immune marker genes strongly suggested that in gastrointestinal tumors, NOTCH3 can control the infiltration and interaction of immune cells in the tumor microenvironment." (PMID 38906903, 2024). "One study reported that HOTAIR silencing with RNAi downregulates neurogenic locus notch homolog protein 3 (Notch3) by down-expression of miR-613 and suppresses tumor growth." (PMID 38559560, 2024). "Studies have shown that an increase in Notch1 and Notch3 is associated with lower DFS in triple-negative and HER-2+ tumors while blockade of Notch 2 and 3 can reduce tumor growth and the frequency of tumor cell initiation." (PMID 39735530, 2024).
tumor (continued). "In CRC, NOTCH3 expression increases with tumor staging and is correlated with worse prognosis, poor overall survival, and CMS4 tumors, which are CAF-enriched and also associated with TGF-β signaling." (PMID 39061234, 2024). "This interaction facilitates the recruitment of the SET1/MLL methyltransferase complex, resulting in histone H3K4 trimethylation and upregulation of oncogenes such as NOTCH3, which in turn promotes tumor growth." (PMID 38744853, 2024). "Conversely, the expression of NOTCH3 appeared to have varying impacts on survival depending on the tumor type, with potential protective or harmful effects." (PMID 39130639, 2024). "The expression of NOTCH3 was analyzed through Western blot, PCR, Oncomine database, and the Tumor Immune Estimation Resource (TIMER) site." (PMID 38906903, 2024). "Consistent with the in vitro results, the inhibitory effects of targeting NOTCH3 on tumor growth and metastasis were counteracted by SPP1 overexpression." (PMID 39557868, 2024). "Through in vitro and in vivo validations, we demonstrated NOTCH3’s contribution to tumor proliferation and invasion, positioning it as a potential therapeutic target." (PMID 39286249, 2024). "Our findings revealed a statistically significant increase in NOTCH3 mRNA expression in tumor tissues and COAD cell lines." (PMID 39286249, 2024). "CCK-8 assays demonstrated that knockdown of NOTCH3 significantly inhibited tumor cell proliferation, and similar results were obtained from colony formation assays." (PMID 39557868, 2024). "In OSCC, NOTCH3 expression in CAFs was positively correlated with micro-vessel density in cancer stroma and tumour size." (PMID 38926351, 2024). "In vivo, subcutaneous xenograft and lung metastasis models showed that targeting NOTCH3 reduced tumor volume and weight and inhibited lung metastasis." (PMID 39557868, 2024). "These analyses provide insights into how CNV and methylation variations influence the expression of FGA and NOTCH3 across various cancer types, potentially contributing to differential tumor behavior and aiding in identifying new therapeutic targets." (PMID 39130639, 2024). "Future research should focus on elucidating the molecular pathways through which FGA and NOTCH3 influence tumor biology and patient survival and validate these biomarkers in larger independent cohorts." (PMID 39130639, 2024). "Subsequently, a subcutaneous xenograft model was established in BALB/c-nude mice, and the results showed that knockdown of NOTCH3 significantly reduced tumor volume and weight, indicating a crucial role of NOTCH3 in tumor growth." (PMID 39557868, 2024). "Overall, these findings indicate that targeting NOTCH3 can inhibit tumor growth and metastasis, suggesting that NOTCH3 is a potential therapeutic target for BLCA." (PMID 39557868, 2024). "These analyses confirmed that NOTCH3 protein levels were significantly elevated in tumor tissues and COAD cell lines, underscoring its potential role in tumorigenesis." (PMID 39286249, 2024). "In conclusion, it is evident that the poor prognosis in a variety of tumour types was strongly correlated with the high expression of NOTCH3." (PMID 38906903, 2024). "We also detected other SVs harboring genes that were expressed in the tumor as the region encompassing NOTCH3 and PKN1 genes and many other genes involved in gene fusions in the tumoral genome." (PMID 39239354, 2024). "The increased expression of NOTCH3 and NOTCH4 in tumor tissues can be linked to their role in promoting cellular proliferation and survival, common features of tumorigenesis." (PMID 39286249, 2024). "In our study, both overall survival (OS) and disease-specific survival (DSS) were included to provide a comprehensive view of patient outcomes related to FGA and NOTCH3 expression across different tumor types." (PMID 39130639, 2024). "The Ocomine21 database provided a pan-cancer investigation of NOTCH3 expression levels, revealing differential NOTCH3 expression in various human tumours." (PMID 38906903, 2024).
tumor (continued). "Collectively, the results confirmed the presence of ac4C modification on NOTCH3 mRNA molecules at the single‐base level, uncovering a signaling cascade involving NAT10 (K823 Khib) and NOTCH3 (ac4C), which regulates fibronectin during tumor metastasis." (PMID 39640362, 2024). "In the LinkedOmics database, CBX2, NOTCH3, HDAC6 and HDAC11 were linked with tumor purity and TNM stage." (PMID 38702698, 2024). "The expression of Ki-67 was markedly lower in the sh-NOTCH3 group compared to the control, indicating a decrease in the proliferative capacity of tumor cells with suppressed NOTCH3 expression in vivo." (PMID 39286249, 2024). "We further assessed the impact of NOTCH3 knockdown and overexpression on tumor growth in vivo using a subcutaneous tumor formation assay in nude mice." (PMID 39286249, 2024). "Notch3 null tumor showed increased proliferation as assessed by immunohistochemistry and RNA-seq signature analysis." (PMID 36854682, 2023). "In parallel, we observed that mice developed mammary gland tumors more rapidly and had a shorter tumor-free survival after Notch 3 inactivation than Notch3-positive tumors." (PMID 36854682, 2023). "Further in vivo studies suggest that NOTCH1 and NOTCH3 inhibition reduces cancer cell proliferation and tumour size." (PMID 37605966, 2023). "In summary, we here show that IGF2BP3 facilitates NOTCH3 mRNA stability to promote Notch3 signaling activation, then enhances the survival and tumor-initiating activity in disseminated tumor cells, leading to robust tumor metastasis in NPC." (PMID 37853162, 2023). "Our findings on the Notch signaling pathway, especially the inducible, increased NOTCH3 expression in cocultures, indicate its critical role in tumor development and possibly acquired drug resistance, according to recent findings." (PMID 38001580, 2023). "Coculturing of oral squamous carcinoma cells with fibroblasts led to induction of both NOTCH3 and αSMA, which interestingly localized in close vicinity of the tumor nests further indicating contact-mediated induction of NOTCH3." (PMID 38269089, 2023). "Nevertheless, the role of the less extensively studied Notch3 in mammary gland tumorigenesis remains debated, as it has been described as on oncogene and as a tumor suppressor." (PMID 36854682, 2023). "Consistently, our study demonstrated that a GSI reduced the tumor initiating ability of NOTCH3-upregulated NPC cells and effectively suppressed NOTCH3-mediated lung metastasis in vivo." (PMID 37853162, 2023). "Notch3 activates cancer stem cells; promotes tumor growth, invasion, metastasis, angiogenesis, and epithelial–mesenchymal transition; and contributes to chemoresistance." (PMID 37958346, 2023). "On the other hand, regarding cell adhesion, epithelial–mesenchymal transition, and motility, NOTCH3 is a tumor suppressor in small-cell lung cancer and a tumor promoter in non-small-cell lung cancer." (PMID 37509254, 2023). "The results showed that interference with Notch3 significantly reduced the proportion of macrophage in tumor tissues." (PMID 36647017, 2023). "Altogether, we provide evidence for a new target of Notch3, which have a major importance in regulating proliferation and tumor initiation." (PMID 36854682, 2023). "It has been demonstrated that the IL6 blockade potentiates the anti-tumor effects of γ-secretase inhibitors in Notch3-expressing can be abrogated by the IL6R blocking antibody tocilizumab in breast cancer." (PMID 37898675, 2023). "Notch3, the third subtype of the Notch family, can regulate tumor maintenance and affect tumor chemotherapy resistance." (PMID 37005430, 2023). "Immunofluorescence staining of tumor samples demonstrated increased CD34+ micro vessels in NOTCH3+CAF containing samples indicative of angiogenesis." (PMID 38269089, 2023). "Whole-exome sequencing revealed 99 somatic mutations including SMARCA4, ARID2, TET2, CDKN2A, WNT7A, NOTCH3 and STAG2, all present both in the primary tumor and in the cell line." (PMID 38201285, 2023).